INS (insulin)
Diseases named in the same sentence as INS in open-access papers (continued):
Sharing a sentence is not in itself a finding about the gene and the disease.
Insulin resistance (continued). "Direct evidence against the mitochondrial dysfunction causes insulin resistance hypothesis is provided by the results of studies in rodents showing that severe impairment of mitochondrial function in muscle results in increased basal and insulin-stimulated muscle glucose uptake." (PMID 21589859, 2011). "The initial response to compensate for insulin resistance is via increased insulin production by pancreatic β-islet cells, leading to hyperinsulinemia." (PMID 22035457, 2011). "Further, associations of the TT genotype with surrogate measures of whole body insulin resistance and insulin sensitivity were observed only in stressed participants." (PMID 21283811, 2011). "Another example is inhibitor kappaB kinase (IKK), which contributes to insulin resistance by phosphorylating protein IRS-1, a protein that has been annotated to be associated with insulin pathway." (PMID 21738677, 2011). "While there are various tests used to detect insulin resistance, fasting insulin levels and the Homeostasis Model Assessment Insulin Resistance Index (HOMA-IR) are widely used in population based studies." (PMID 21901158, 2011). "In insulin resistance, glucose uptake is reduced in peripheral, insulin-sensitive tissues, whereas endogenous glucose production is increased, resulting in hyperglycemia." (PMID 24250430, 2011). "In the prediabetic stage this insulin resistance is initially met by a compensatory increase in insulin production by pancreatic β-cells sufficient to maintain fasting euglycemia." (PMID 21869886, 2011). "It is reported that TRB3 impairs insulin signalling through the inhibition of Akt phosphorylation and plays a role in insulin resistance." (PMID 21492415, 2011). "We found that a very small reduction in BMI z-score (≥ 0.00-< 0.10) improved insulin and insulin resistance." (PMID 21619652, 2011). "Impaired insulin action (i.e. insulin resistance) in liverand skeletal muscle as well as reduced pancreatic beta-cell insulin secretion arepathogenic for type 2 diabetes." (PMID 21573217, 2011). "Defects in the insulin signaling cascade leading to impaired glucose utilization are believed to play a key role in the pathogenesis of insulin resistance." (PMID 19233878, 2011). "In our studies in order to access insulin resistance we focused on the fasting levels of glucose and insulin." (PMID 21781316, 2011). "The activation of these pathways leads to interference with insulin signaling leading to insulin resistance, an early event in obesity." (PMID 22035457, 2011). "A World Health Organization (WHO) consensus group concluded that the insulin sensitivity index of the lowest 25% of a general population can be considered as an insulin resistance state." (PMID 21251282, 2011). "The question remains, however, does insulin in the context of insulin resistance/hyperinsulinemia exacerbate or mitigate the existing conditions of TNFα-stimulated VCAM-1 expression?" (PMID 22093181, 2011). "Means and SD for variables related to the OGTT, insulin, and homeostatic model insulin resistance at 8–12 and 26–28 wk gestation." (PMID 21610860, 2011). "IGF-1 deficiency mice were very insulin insensitive, while administration of IGF-1 shows the insulin resistance improvement." (PMID 21689475, 2011). "Mean and standard error of the mean of postoperative serum glycaemia, insulin, and insulin resistance (HOMA-IR) in the two groups." (PMID 21668975, 2011). "The CO group showed greater serum insulin (19.9 ± 3,99 versus 10.7 ± 2.9 μU/mL; p = 0.049) and insulin resistance (5.7 ± 1.1 versus 2.7 ± 0.7; p = 0.03) when compared to CO group postoperatively." (PMID 21668975, 2011). "In an insulin resistance condition, there is a reduced sensitivity to insulin, which leads to overproduction of insulin (hyperinsulinemia)." (PMID 22654727, 2011).
Insulin resistance (continued). "BER can also improve insulin resistance and exerts an insulin-independent glucose-lowering effect, stimulating insulin secretion and sensitizing insulin activity, inducing glycolysis, and increasing glucose transport and uptake activity." (PMID 22152059, 2011). "Insulin resistance is characterized by a diminished reaction of insulin-sensitive tissues and a marked decrease in glucose metabolism in response to insulin." (PMID 21603234, 2011). "As expected, the sedentary diabetic (fa/fa) rats showed significantly (P < 0.001) higher values of glucose (+359%), HbA1c (+272%), and insulin (+270%), together with higher insulin resistance (HOMA-IR), when compared with their lean sedentary counterparts." (PMID 22174491, 2011). "We found that these auto-antibodies neutralize PDI, decrease insulin degradation and correlate with higher insulin levels and insulin resistance." (PMID 21949836, 2011). "Duplain and Sydow using glucose clamp studies reported insulin resistance in eNOS ko mice and increased insulin sensitivity in DDAH transgenic mice." (PMID 21781316, 2011). "A major contributor to the development of insulin resistance (and thus higher levels of insulin) is the overabundance of free fatty acids produced in adipose tissue." (PMID 22035351, 2011). "Insulin and glucose tolerance tests of 15-week-old females showed insulin resistance and slight glucose intolerance in Tw/+ mice, consistent with data for other obese mice with hyperinsulinemia." (PMID 21980308, 2011). "The progression towards type 2 diabetes depends on the allostatic response of pancreatic beta cells to synthesise and secrete enough insulin to compensate for insulin resistance." (PMID 22208362, 2011). "Taken together, our findings do not support a model in which a genetic polymorphism in the putative insulin response element of APOC3 leads to increased accumulation of TG in the liver, which in turn results in insulin resistance." (PMID 21274868, 2011). "As offspring age, initial insulin sensitivity is replaced with insulin resistance in later adulthood." (PMID 22194901, 2011). "Rs439401 TT-genotype also associated positively with surrogate measures of insulin resistance (HOMA-IR; OR = 1.21 [1.03; 1.41]) and inversely with insulin sensitivity (Stumvoll index; OR = 0.90 [0.82; 0.99], BIGTT-SI; OR = 0.60 [0.43; 0.85]) in stressed men." (PMID 21283811, 2011). "Regardless of HIV, basal myocardial glucose utilization was blunted in the presence of elevated plasma insulin in men with metabolic complications that included peripheral insulin resistance (HOMA-IR)." (PMID 22151886, 2011). "As long as the β-cells are able to augment insulin secretion to compensate insulin resistance, glucose tolerance remains normal." (PMID 21276212, 2011). "Type-2 diabetes results from the development of insulin resistance and a concomitant impairment of insulin secretion." (PMID 21949805, 2011). "Type 2 diabetes is characterized by an insensitivity of peripheral tissues to the action of insulin, termed insulin resistance." (PMID 20008903, 2011). "In accordance, both glucose and insulin tolerance tests revealed that animals fed WD/S had impaired glucose tolerance and systemic insulin resistance." (PMID 21966444, 2011). "All these metabolic alterations associated with type 2 diabetes result from a relative insufficiency of insulin to overcome peripheral insulin resistance." (PMID 21785636, 2011). "As already established, in accordance with eNOS phosphorylation studies, conditions simulating insulin resistance (HG and Gluc-N) markedly inhibited NO production induced by insulin in HUVECs (p<0.05)." (PMID 21297971, 2011). "Insulin resistance is a concept generally used to describe reduced insulin signaling in spite of high levels of insulin in the body." (PMID 22163304, 2011).
Insulin resistance (continued). "Insulin resistance and reduced insulin levels decreased PI3K-NO-dependent signaling, which trigger imbalance between NO and endothelin-1 responsible for impaired vascular endothelium-dependent relaxation." (PMID 25392740, 2011). "An alteration in insulin action in the brain, named “cerebral insulin resistance”, is responsible for overeating and the development of obesity." (PMID 21589921, 2011). "Insulin resistance is a complex disorder influenced by lifestyle and genetic factors where the natural hormone, insulin, becomes less effective at lowering high blood sugar." (PMID 21901158, 2011). "An index for insulin resistance is calculated according to the Homeostasis Assessment Model for insulin resistance (HOMA-IR) formula: (fasting insulin (mU/mL) × fasting glucose (mmol/L)) / 22.5." (PMID 21548919, 2011). "The antidiabetic action of cinnamon exerted by insulin secretagogue action and insulin resistance amelioration has been previously reported." (PMID 21711570, 2011). "Insulin resistance was determined with the fasting glucose (mmol/L) to insulin (mIU/L) ratio and HOMA-IR (Homeostasis model assessment-Insulin resistance)." (PMID 26396568, 2011). "In the present study, the elevated insulin levels in IDFP-treated animals following glucose administration indicate that the glucose intolerance likely results from severe insulin resistance." (PMID 22073164, 2011). "The homeostasis model assessment of insulin resistance suggests that FOS supplementation improves insulin sensitivity measured in the fasting state in n-3/- mice, even if it was not statistically significant (p = 0.06)." (PMID 21707971, 2011). "We next assessed the effects of NKT deletion on obesity-induced insulin resistance, using insulin (ITT) and glucose tolerance tests (GTT)." (PMID 21674035, 2011). "The physiologic result of insulin resistance is thus an increase in insulin secretion by the pancreatic β-cells in order to compensate for reduced insulin action." (PMID 22110473, 2011). "PIs have been shown to increase insulin resistance and reduce insulin secretion, by interfering with GLUT-4 mediated glucose transport." (PMID 21232158, 2011). "Thiazolidinediones improve insulin resistance by enhancing insulin action in skeletal muscle, liver and adipose tissue through a mechanism that is not yet fully understood." (PMID 22098677, 2011). "From the viewpoint of PPARα activation improving insulin sensitivity, the observations of PPARα agonists /activators downregulating TF expression also likely point to positive TF function(s) in insulin resistance involving inflammatory diabetes development." (PMID 21941675, 2011). "The principal site of glucose uptake under insulin-stimulated conditions is skeletal muscle, being considered a primary site for insulin resistance." (PMID 21489269, 2011). "The collusion of these stimuli leads to interference with insulin signaling and insulin resistance, which is an early step on the path to type 2 diabetes." (PMID 22035457, 2011). "We observed a likely association of insulin sensitivity with mode of ACTN3 expression, with 42.2% of the individuals falling in the higher expressed mode which was associated with insulin resistance." (PMID 21299892, 2011). "Insulin resistance and elevated insulin levels are features of severe disease in early RA, if untreated, and are driven primarily by systemic inflammation." (PMID 21061259, 2011). "It has been reported that the pathophysiological changes of GDM are similar to those observed in T2D, which is characterized by peripheral insulin resistance accompanied by an insulin secretory defect." (PMID 22096510, 2011). "Inhibition of miR-320 in insulin resistance 3T3-L1 adipocytes was found to improve insulin sensitivity and insulin-stimulated glucose uptake via modulation of p85 expression, phosphorylation of Akt and GLUT4 protein levels." (PMID 21506921, 2011).
Insulin resistance (continued). "We assessed the association of the mode of expression with pre-diabetic traits (body mass index/percent body fat, insulin resistance, and insulin secretion), in the eight confirmed bimodal genes." (PMID 21299892, 2011). "The present study documents that myricetin (3,5,7,3′, 4′, 5′-hexahydroxyflavone) ameliorates insulin resistance by enhancing β-endorphin production in insulin-resistant rats." (PMID 21785619, 2011). "In the dairy group, the serum triglycerides, insulin levels and insulin resistance remained significantly better than baseline values until the 12 month follow-up." (PMID 22299005, 2011). "Although the euglycemic insulin clamp test is currently the best and most accurate technique for assessing insulin sensitivity, the fasting insulin level was used as the marker for insulin resistance in this current study." (PMID 22129309, 2011). "DBT is therefore proposed as potentially useful adjuvant therapy for patients with insulin resistance and/or the patients who wish to increase insulin sensitivity." (PMID 19233878, 2011). "In order to prevent the formation of insulin resistance, agents and/or methods for enhancing insulin sensitivity become important topic recently." (PMID 21754922, 2011). "Several mechanisms have been proposed for such effects, including enhanced immune function, decreased inflammation, reduced insulin levels and insulin resistance, and higher vitamin D levels." (PMID 21304525, 2011). "The expression and serum levels were normalized by treatment with insulin or pioglitazone, suggesting that vaspin exerts a defensive action against insulin resistance." (PMID 21526992, 2011). "To address the potential effect of oral agents, we have specifically excluded individuals on thiazolidinediones, which are known to have the most impact on insulin resistance, to minimize the impact of oral agents on measured insulin sensitivity." (PMID 22164267, 2011). "In rodents, models of gestational diabetes produce offspring with glucose intolerance, impaired insulin secretion, insulin resistance and increased adiposity." (PMID 21494686, 2011). "Sixty-two percent of hyperglycemic children were insulin-resistant, 17% had β-cell dysfunction, and 21% had both insulin resistance and β-cell dysfunction." (PMID 21276273, 2011). "Compared with a number of reports on the role of IL-1β as an endogenous mediator of insulin resistance, studies on the relationship between IL-1α and insulin signaling and obesity are rare." (PMID 22216303, 2011). "The causes of postprandial hyperglycemia are influenced by many factors which include a rapid flux of glucose from the gut, impaired insulin release, endogenous glucose production by the liver and peripheral insulin resistance." (PMID 21701577, 2011). "Fasting glucose and insulin levels were used to calculate a homeostasis model assessment of insulin resistance and quantitative insulin sensitivity check index quantitative insulin sensitivity check index." (PMID 21218504, 2011). "FFA play a role in both the cellular and molecular mechanisms of insulin resistance, because they are a determinant of the membrane properties that affect insulin sensitivity and act as physiological signaling molecules that induce insulin resistance." (PMID 23675238, 2011). "As the insulin resistance aggravated gradually, β cell had the responsibility for the compensate of defects in insulin secretion and insulin action so as to maintain normal glucose homeostasis." (PMID 22022381, 2011). "Transgenic mice, with 99% less white adipose tissue and inactive brown adipose tissue, developed insulin resistance manifested by threefold elevated plasma glucose levels and 50- to 400-fold elevated insulin levels." (PMID 21811683, 2011). "Insulin resistance was consistently higher in males than in females, which is in accordance with the human situation with women considered to be more insulin sensitive than men." (PMID 21070590, 2011).
Insulin resistance (continued). "Since insulin secretion is dependent on the actual insulin sensitivity, we compared the disposition index, an integrated measure of the ability of the β-cells to compensate for insulin resistance, between the two groups." (PMID 21408112, 2011). "Insulin resistant animals compensate for their insulin resistance and maintain normal glucose levels by increasing insulin secretion." (PMID 21998599, 2011). "Mean and standard error of the mean of the difference between preoperative and postoperative values of serum glycaemia, insulin, and insulin resistance (HOMA-IR) in the two groups." (PMID 21668975, 2011). "Changes in histone acetylation appear to have a central role in insulin function and insulin resistance." (PMID 21655096, 2011). "Our present study showed that amylin and insulin were both elevated in obesity and insulin resistance, which is consistent with previous reports." (PMID 21935471, 2011). "Since increased body fat is associated with insulin resistance, we assessed if the greater weight gain of D2KO mice would lead to differences in glucose handling and insulin responsiveness." (PMID 21698184, 2011). "Derived indices for insulin resistance and insulin sensitivity revealed significant results, in S-49." (PMID 21283811, 2011). "Excessive fat deposition in insulin effector cells, such as hepatocytes, muscle cells, and adipocytes, can decrease the sensitivity of these cells to insulin and ultimately result in insulin resistance." (PMID 22582147, 2011). "Despite the differences in defining insulin resistance observed in each study, in regard to the characteristics of insulin resistant subjects, consistent results have been mostly proposed." (PMID 22025967, 2011). "Second, insulin resistance was assessed by measuring fasting serum insulin level, C-peptide, and calculating HOMA-IR." (PMID 21196652, 2011). "The major findings from this study are the effects of variation within IL-18 using combined haplotypes analysis, on insulin levels and estimates of insulin resistance." (PMID 20227263, 2011). "Cytokines and ROS can contribute to insulin resistance and the resultant excess circulating glucose, free fatty acids and insulin can further induce inflammation." (PMID 21696633, 2011). "Insulin and glucose tolerance tests showed insulin resistance and slight glucose intolerance in KIG/KIA mice." (PMID 21980308, 2011). "Changes in BMI were directly correlated with changes in insulin levels and in insulin resistance as measured by HOMA-IR." (PMID 21676224, 2011). "Although this finding would be in general agreement with the fetal-insulin hypothesis, it is paradoxical compared to a recent study in a large Danish cohort as another ‘birth weight-lowering’ (rs11708067) variant was associated with reduced adult insulin resistance." (PMID 21712988, 2011). "Based on this, a recently prevailing view that a mild to moderate level of ethanol consumption reduces the level of insulin and/or insulin resistance is noteworthy." (PMID 21845171, 2011). "Rosiglitazone administration to HIV-infected subjects with insulin resistance significantly improved skeletal muscle insulin sensitivity, as previously reported for a subgroup of these subjects." (PMID 21559208, 2011). "Insulin resistance is characterized by reduced responsiveness of target tissues (liver, skeletal muscle, adipocytes) to normal circulating levels of insulin, followed by a progressive decline in insulin secretion from the pancreas." (PMID 21774832, 2011). "Use of insulin sensitizers, such as Metformin, would be the second best approach to improving insulin resistance." (PMID 21668983, 2011). "HFD was associated with a significant increase in plasma levels of glucose and insulin suggestive of systemic insulin resistance, and these parameters returned to baseline within 2 weeks of resuming normal chow." (PMID 21479224, 2011).